LIF (LIF interleukin 6 family cytokine)
Diseases named in the same sentence as LIF in open-access papers (continued):
Sharing a sentence is not in itself a finding about the gene and the disease.
cancer (continued). "The RT-qPCR analysis indicated that mRNA expression of CAF markers (ACTA2, TAGLN, and LIF) was increased when fibroblasts were educated by cancer cells (gray bars, cancer-EV + CAF)." (PMID 39261905, 2024). "LIF overexpression promotes cancer cell proliferation, metastasis, immune evasion, stemness, and metabolic reprogramming, all of which contribute to tumorigenesis." (PMID 38245529, 2024). "In pancreatic ductal adenocarcinoma (PDAC), KRAS mutations upregulate LIF through the MEK/ERK cascade, thereby promoting cancer malignancy." (PMID 39169307, 2024). "Future studies are needed to better understand the overexpression of LIF in cancers and as well as the contribution of these LIF regulators to cachexia." (PMID 38245529, 2024). "Third, our results provide experimental evidence that LIF derived from cancer cells or CAFs contributes to CSC stemness in HNSCC." (PMID 39206755, 2024). "In the present study, we report that the transcriptome analysis of cancer tissues from a cohort of locally advanced GCs express a dysregulated expression of LIF/LIFR and FGFR4." (PMID 37945798, 2024). "Activation of this pathway in both CAFs and cancer cells is needed to increase the expression of both LIF and GM-CSF." (PMID 39262776, 2024). "Mechanistically, myMAFs are induced through a STAT3-dependent mechanism driven by macrophage-derived progranulin and cancer cell-secreted leukaemia inhibitory factor (LIF)." (PMID 38678021, 2024). "Using genetic and pharmacological approaches, we reveal that active JAK/STAT signalling, driven by complementarity of progranulin and cancer cell-derived LIF, promotes myMAF activation and function." (PMID 38678021, 2024). "Macrophages and cancer cells promote pSTAT3+myMAF activation, via progranulin and LIF mediated JAK/STAT signalling." (PMID 38678021, 2024). "Since many different factors can contribute to cachexia, future studies are needed to validate the relevance of our findings in cancer mouse models and human patients, especially those cancers with LIF overexpression." (PMID 38245529, 2024). "Significantly, LIF knockout (KO) in these cells blocked the cancer-induced activities in the signature brain regions, such as the PVN and Me5-L/-R." (PMID 38467743, 2024). "LIF/LIFR axis has been connected to numerous hallmarks of cancer, including proliferation, avoiding immune system damage, chemoresistance, and overall patient survival." (PMID 38789520, 2024). "Taken together, our findings strongly suggest that LIF either produced by cancer cells or CAFs contributes to HNSCC CSC maintenance in an autocrine/paracrine manner." (PMID 39206755, 2024). "For example, endoplasmic reticulum stress and hypoxia are a few of the hallmarks of TNBC and hypoxia induces LIF expression in human cancer cells." (PMID 39518071, 2024). "Taken together, our results identify LIF as a key cancer cell derived factor, which combined with progranulin induces a pSTAT3+myMAF phenotype in vitro." (PMID 38678021, 2024). "To substantiate the presence of LIF‐SE in HNSCC clinical samples, we performed H3K27ac ChIP‐seq in freshly collected HNSCC (HNSCC1 and HNSCC2) and normal oral mucosa (NOM) samples and identified similar LIF‐SE loci in primary cancer samples only." (PMID 39206755, 2024). "Considering the significance of LIF/LIFR signaling in cancer, our team recently has created an inhibitor for LIFR, designated as EC359." (PMID 39518071, 2024). "Future research exploiting mouse models with the neuron-specific deletion of Lifr will help delineate how LIF mediates brain responses to peripheral cancers." (PMID 38467743, 2024).
cancer (continued). "In the presence of IgG, cancer cell CM with progranulin induced the expression of myMAF genes, including Spp1, Acta2, and Postn, while the neutralisation of LIF partially suppressed this induction." (PMID 38678021, 2024). "LIF and LIFR show an opposite modulation in the cancer tissues, thus while LIF expression is higher in PDAC in comparison with the adjacent normal tissue, the expression of LIFR is subject to opposite modulation." (PMID 36998446, 2023). "Establishing the role of LIF in the TIME of childhood cancers potentially opens up the possibility of combined LIF inhibition and anti-PD-L1 immunotherapy." (PMID 37013636, 2023). "This reduction in LIF suggested a potential cancer-suppressive effect of TKI treatment, as well as a potential for cardiovascular damage." (PMID 37103052, 2023). "In both mouse and human PDAC tissues, LIF mRNA was abundant in specifically activated CAFs, especially in those adjacent to cancer cell nests, reaffirming activated PSCs as the major LIF-producing cells." (PMID 37174079, 2023). "In another study, it was found that CAFs can induce cancer stemness and gemcitabine resistance through leukemia inhibitory factor (LIF), which is promoted by circFARP1 specifically expressed in CAFs via direct binding to caveolin 1 (CAV1)." (PMID 37819576, 2023). "Given the important role of the LIF axis in the invasiveness of cancer cells, we examined the effect of EC359 in terms of reducing the invasion of Type II ECa cells." (PMID 38139260, 2023). "Although other IL-6 family members have been shown to regulate the metastasis of multiple cancer types, the role of LIF and LIFR remains challenging to access." (PMID 36925915, 2023). "The gp130 family members, IL-11, IL-6, OSM, and LIF (upregulated in the LM) potentially impact skeletal muscle wasting by inducing the STAT3 signaling pathway in the preclinical model of cancer cachexia." (PMID 36774484, 2023). "A third cytokine that signals through gp130, LIF, also has been shown to play a role in the pathogenesis of cancers such as pancreatic cancer." (PMID 38022653, 2023). "Recently, we have also demonstrated a Hippo-dependent anti-proliferative and anti-metastatic effect of LIF in a subset of gastric-derived cancer stem cells." (PMID 38137514, 2023). "Previous reports, including ours, showed that LIF activates AKT in cancer cells, which raises the possibility that AKT activation by LIF contributes to the promoting effect of LIF on Glut1 PM translocation." (PMID 35440095, 2022). "Reviewing the literature on the potential effects of LIF in physiological and pathological conditions reinforces studies that have found similar effects of LIF within various cancer types." (PMID 35204717, 2022). "Studies of the mouse C26 model of colon cancer have established LIF and its related cytokine, OSM, as key causal cytokines of cancer-related skeletal muscle atrophy." (PMID 35204717, 2022). "Within cancers, LIF mRNA is expressed by epithelial carcinoma cells and surrounding stromal cells (fibroblasts, monocytes, T-cells, and macrophages)." (PMID 35204717, 2022). "LIF is involved in the interaction between cancer cells and cancer-associated fibroblasts (CAF), forming a feedback loop between cancer cells and CAF." (PMID 35740622, 2022). "LIF is over-expressed in the cancer cells and stromal cells of various tumors, promoting the malignant development of tumors via the autocrine and paracrine systems." (PMID 35740622, 2022). "LIF, a pleiotropic cytokine of the interleukin 6 families, participates in numerous vital biological processes, including cell differentiation, cancer metastasis, relapse, and drug resistance." (PMID 35654787, 2022). "Among those downregulated, CXCL1, CCL2, CXCL8, CTGF, LIF, and IL-6 are known to be involved in fibrosis or cancer stroma." (PMID 36289649, 2022).
cancer (continued). "Increasing evidence demonstrates tumor-promoting role of LIF in cancer and its potential in mediating therapy resistance and increasing self-renewal capacity of cancer-initiating cells." (PMID 35773731, 2022). "The LIFR has also been investigated within cancers, where like LIF, its expression is often dysregulated compared to healthy tissue." (PMID 35204717, 2022). "LIF is involved in a number of key processes in cancer growth and progression, including immune tolerance, chemotherapy and radiation resistance, maintenance of cancer stem cell-like phenotypes, and EMT." (PMID 35992780, 2022). "LIF also has a significant role in enriching and maintaining cancer stem cells, epithelial to mesenchymal transition, de-differentiation, and re-differentiation of cancer cells." (PMID 36329823, 2022). "Different cytokines are secreted by CAFs to promote cancer growth, such as TGFβ, leukemia inhibitory factor (LIF), and HGF." (PMID 36077813, 2022). "Then, using PDEs described as, TGFβ and LIF signals from cancer cells as well as TGFβ and CXCL12 molecules from CAFs release into the TME." (PMID 36171274, 2022). "The LIF/LIFR signaling has been identified as a potential therapeutic target in the treatment of several cancers." (PMID 35847866, 2022). "Our results demonstrate that while LIF promotes cancer cell proliferation and migration in a JAK-STAT3–dependent manner, these features are reversed by mifepristone." (PMID 36359879, 2022). "The functional role of LIF in TME-mediated cancer progression has been well characterized, but little is known about its upstream modulators in CAFs." (PMID 35045883, 2022). "A previous study showed that although LIF expression was upregulated in both cancer cells and stromal cells of PDAC, it was only secreted from stromal cells, suggesting the specific mechanism of LIF secretion in the TME." (PMID 35045883, 2022). "LIF signalling in cancer cells is mediated by its binding to the LIFR complex and JAK/STA3 phosphorylation." (PMID 36359879, 2022). "LIF has been found to be overexpressed in more types of cancers in the past and has played a carcinogenic role." (PMID 35992780, 2022). "Additional pharmacologic mechanisms have been investigated as methods of preventing LIF-mediated effects within cancers other than targeting LIF itself or the LIFR." (PMID 35204717, 2022). "As expected, silencing CAV1 in CAFs attenuated their ability to promote pancreatic cell proliferation, colony formation, sphere formation, and apoptosis resistance, similar to the cancer phenotypes induced by circFARP1 or LIF depletion." (PMID 35045883, 2022). "Factors related to skeletal and cardiac muscles (myokines and cardiokines) or factors secreted by cancer and cancer-associated immune cells (TGF-β, DAMPSs, and LIF) trigger a cascade of processes that ultimately result in cachexia." (PMID 35457471, 2022). "This review aims to link physiological and pathological roles of LIF to roles that it has been found to have in cancers, and to point out that additional research into the drivers, mechanisms, and downstream effects of LIF signaling is warranted." (PMID 35204717, 2022). "An unrelated Phase I study investigated LIF as a potential therapeutic for rescue of hematopoietic cells in patients with advanced cancer before and during chemotherapy treatment." (PMID 35204717, 2022). "LIF can function as upstream mediator of JAK1/STAT3 signaling in preventing differentiation of cancer cells." (PMID 35773731, 2022). "Meanwhile, in CRC, low expression of miR-637 leads to activation of the Jak/STAT3 signaling pathway through the lncAMPC/miR-637/LIF axis, thereby promoting inflammation and cancer cell migration and invasion." (PMID 36175921, 2022). "The main aim of this review is to increase the understanding of the effects of LIF in cachexia and to provide new insights into the treatment of cancer cachexia." (PMID 35740622, 2022).
cancer (continued). "The expression of LIF in adipocytes adjacent to cancer cells were increased significantly (as the black arrow points out), while the adipocytes in normal breast tissue did not express LIF." (PMID 35280694, 2022). "MIA PaCa-2 cells and PDAC tissue express LIF that acts as an autocrine factor to promote cancer cell proliferation." (PMID 36359879, 2022). "The findings of the current study show that LIF promotes cancer-induced muscle wasting by modulating JAK/STAT and MAP-kinase pathways." (PMID 34838029, 2021). "Recently published studies indeed support oncogenic role of LIF/LIFR signaling in cancer progression." (PMID 34716410, 2021). "LIF also enhances cancer cell proliferation, favors the development of a pro-invasive phenotype, and promotes chemotherapy and radiotherapy resistance." (PMID 33741032, 2021). "Blockade of LIF by neutralizing antibodies is shown as an attractive approach in improving cancer therapeutic outcomes." (PMID 34400617, 2021). "On a final note, very few studies (both in cancer and in other fields) make a clear distinction between the intracellular and secreted forms of LIF." (PMID 34395259, 2021). "IL-1 induces LIF expression and downstream JAK/STAT activation to generate inflammatory CAFs in pancreatic cancer, thus promoting cancer progression, chemoresistance and other cancer-associated systemic effects, such as cachexia and immune suppression." (PMID 34976805, 2021). "Leukemia inhibitory factor receptor (LIFR) and its ligand LIF play a major role in cancer progression, metastasis, stemness, and therapy resistance." (PMID 34400617, 2021). "Hopefully, this review will act as an aid to any researcher looking to further develop our emerging perspectives of LIF and its receptor in cancer." (PMID 34395259, 2021). "These are just a small sample of many unanswered questions when it comes to LIF and LIFRβ in cancer, many of which are enticing avenues of research." (PMID 34395259, 2021). "Preliminary preclinical data on the role of LIF in cancer progression have prompted the design of a humanised anti-LIF monoclonal antibody (MSC-1)." (PMID 33630157, 2021). "Interleukin-6-class cytokines (e.g., IL-6, LIF, OSM, IL-11) are among few growth factors that are considered master regulators of cancer-associated inflammation." (PMID 34491463, 2021). "In light of these interesting preliminary results, a phase I clinical trial of MSC-1 in high LIF-expressing cancer patients has been launched in the US, Canada and Spain (NCT03490669)." (PMID 33630157, 2021). "Clearly, LIF and the LIFRβ have relevant connections to cancer growth and metastasis that warrant additional research and definition." (PMID 34395259, 2021). "One of the best studied properties of LIF is its role as a pro-survival, stem-cell factor that drives anchorage-independent growth and the formation of cancer spheroids." (PMID 33846527, 2021). "When YAP was inhibited via shRNA, the effect of LIF-LIFR signaling on cancer growth and migration was lost." (PMID 34395259, 2021). "We also noticed that growth factors, including NOV, BMP4, MDK, GDF15, VEGFC, NTF3, and LIF, were previously reported to promote cancer development, especially in cancer metastasis in various cancers, including CRC." (PMID 34440086, 2021). "Unfortunately, two promising phase III clinical trials with inhibitors of JAK/STAT3 (i.e. the JAK1/JAK2 inhibitor ruxolitinib and the STAT3 inhibitor napabucasin), the leading effector pathway of LIF stimulation in cancer cells, were stopped due to futility." (PMID 33630157, 2021). "In many cancer types, including melanomas, skin, kidney, prostate, and pancreatic cancers, a LIF signal is expressed at high levels, inducing an autocrine/paracrine cell proliferation, like in embryo implantation." (PMID 34295890, 2021). "LIF also plays a role in cancer because it favors the immunosuppressive features of the TME by increasing CCL-2 and decreasing CXCL-9 release by TAMs." (PMID 33741032, 2021).
cancer (continued). "This should be unsurprising at this point, considering how this has been a recurring motif for LIF not only in cancer but physiologically as well." (PMID 34395259, 2021). "The findings indicated that miR-29c was negatively correlated with the cachectic phenotype, and the miR-29c-LIF axis is a potential therapeutic target for cancer cachexia." (PMID 34838029, 2021). "Further, CAFs regulate cancer stem cells through the LIF/LIFR pathway and can be an anticancer therapy target." (PMID 34947829, 2021). "The IL-6 family cytokine LIF and its receptor subunit LIFRβ have come to represent a challenge to understanding the role of inflammatory cytokines in cancer." (PMID 34395259, 2021). "In contrast to what has been reported for acute myeloid leukemia, in PDAC LIF paracrine activity induces cancer stem cell self-renewal and cell differentiation arrest." (PMID 33630157, 2021). "LIF role in chemoresistance mechanisms was studied more extensively in other cancer types than PDAC." (PMID 33630157, 2021). "Inflammatory factors such as interleukin-6 (IL-6), tumor necrosis factor (TNF)-α, and leukemia inhibitory factor (LIF) are commonly examined for their roles in cancer-induced muscle wasting." (PMID 34395422, 2021). "This is an excellent example of the challenge in discerning the role of LIF and LIFRβ in cancer, as even in a single cell line their effects are debated." (PMID 34395259, 2021). "Although other members of the IL-6 family have been shown to be involved in the metastasis of multiple types of cancer, the role of LIF and LIFR has been challenging to determine." (PMID 34395259, 2021). "Other cytokines, specifically IL-6 and OSM, clearly have more profound effects in cancer through STAT3—this has left LIF in the proverbial wayside, as more potent activators of STAT3 have been targeted for study." (PMID 34395259, 2021). "While this work highlighted a paracrine role of LIF produced by stellate cells on cancer cell differentiation and epithelial-mesenchymal transition, it should be noted that pancreatic cancer cell lines express active STAT3." (PMID 34491463, 2021). "Further, LIF blockade causes existing PDAC tumors to become less aggressive and more differentiated, likely due to loss of cancer stem cells." (PMID 33846527, 2021). "Despite significant advances in our knowledge of how inflammation drives cancer progression and metastasis, LIF and LIFRβ provide particularly poignant demonstrations of how much there is to learn about the processes involved." (PMID 34395259, 2021). "It is this very concept of functional redundancy, in addition to the fact the LIF and LIFRβ exhibit such clear polyfunctionality, that make the pair so obscure within the context of our understanding of cancer." (PMID 34395259, 2021). "LIF as an immunomodulator/suppressor in cancer represents an important potential target for treatment." (PMID 34395259, 2021). "This is relevant in that it shows outcomes of LIF signaling are markedly different across tissue types—a concept that will be developed further as we begin to discuss LIF in cancer." (PMID 34395259, 2021). "Accumulating evidence has suggested that LIF plays a role in supporting cancer evolution as a regulator of cell differentiation, renewal and survival." (PMID 33630157, 2021). "Cancers where LIF or LIFRβ are demonstrated to have an effect on human cancer cells in vitro and/or in vivo." (PMID 34395259, 2021). "LIF is involved in a number of key processes underlying cancer growth and progression including immunotolerance, PNI, chemo and radioresistance, cancer stem cell-like phenotype maintenance, EMT, and TME development." (PMID 33630157, 2021). "LIF is a multi-functional member of the interleukin-6 family of cytokines, and plays an intricate role in cancer." (PMID 34838029, 2021). "LIF elicits proliferation of different kinds of cancers such as multiple myeloma, colon, prostate and breast cancers." (PMID 32651426, 2020).